FFAR1 (free fatty acid receptor 1)
Description:
G protein-coupled receptor for medium and long chain saturated and unsaturated fatty acids that plays an important role in glucose homeostasis. Fatty acid binding increases glucose-stimulated insulin secretion, and may also enhance the secretion of glucagon-like peptide 1 (GLP-1). May also play a role in bone homeostasis; receptor signaling activates pathways that inhibit osteoclast differentiation (By similarity). Ligand binding leads to a conformation change that triggers signaling via G proteins that activate phospholipase C, leading to an increase of the intracellular calcium concentration. Seems to act through a G(q) and G(i)-mediated pathway. Mediates the anti-inflammatory effects of omega-3 polyunsaturated fatty acids (PUFAs) via inhibition of NLRP3 inflammasome activation.
Synonyms: GPR40; FFA1R; GPCR40
Tractability: Small molecule: a drug acting on it is in phase 2 or 3 trials; a structure with a bound ligand is known; a high-quality ligand is known; it belongs to a druggable protein family. Antibody: UniProt places it where antibodies can reach, with high confidence; its Gene Ontology location is reachable by antibodies, with high confidence; UniProt predicts a signal peptide or a membrane-spanning region; the Human Protein Atlas places it where antibodies can reach. PROTAC: a small molecule that binds it is known.
Target class: Family A G protein-coupled receptor; Small molecule receptor (family A GPCR); Membrane receptor; Free fatty acid receptor; Lipid-like ligand receptor (family A GPCR)
Chemical probes: AM-1638 (high quality), AM-4668 (high quality), AM-5262 (high quality), AM-6226 (high quality), AMG-837 (high quality), BI-2081 (high quality), DS-1558 (high quality), FASIGLIFAM (high quality), GPR40ant39 (high quality), GW1100 (high quality), GW9508, TP-051 (high quality), TUG-469 (high quality)
Gene: Protein-coding gene on chromosome 19 (35,347,902 to 35,353,864, forward strand). Ensembl gene ENSG00000126266.
Subcellular location: Cell membrane
Subcellular location (Human Protein Atlas): Plasma membrane
Pathways (Reactome):
Metabolism of proteins: Synthesis, secretion, and inactivation of Glucagon-like Peptide-1 (GLP-1); Synthesis, secretion, and inactivation of Glucose-dependent Insulinotropic Polypeptide (GIP)
Signal Transduction: Free fatty acid receptors; G alpha (q) signalling events
Metabolism: Fatty Acids bound to GPR40 (FFAR1) regulate insulin secretion
Gene Ontology:
Molecular function: bioactive lipid receptor activity; G protein-coupled receptor activity
Biological process: negative regulation of interleukin-1 beta production; positive regulation of calcium ion transport; positive regulation of cytosolic calcium ion concentration; response to fatty acid; G protein-coupled receptor signaling pathway; positive regulation of insulin secretion; phospholipase C-activating G protein-coupled receptor signaling pathway
Cellular component: plasma membrane; membrane
Genetic constraint (gnomAD): Loss-of-function variants: 1 observed, 0.66 expected, observed/expected ratio (o/e) 1.51, 90% interval 0.31 to 1.92. That is too few expected variants to judge how well the gene tolerates losing a copy. Missense variants: 424 observed, 352.55 expected, observed/expected ratio (o/e) 1.2, 90% interval 1.11 to 1.3. Synonymous variants: 216 observed, 177.37 expected, observed/expected ratio (o/e) 1.22, 90% interval 1.09 to 1.36.
Homologues: Orthologues: chimpanzee FFAR1 (99% identical), macaque FFAR1 (96% identical), dog FFAR1 (85% identical), mouse Ffar1 (83% identical), rat Ffar1 (81% identical), guinea pig Ffar1 (80% identical). Paralogues in human: GPR42 (31% identical), FFAR3 (31% identical), FFAR2 (27% identical), P2RY6 (23% identical), GPR31 (23% identical), OXER1 (21% identical), P2RY4 (20% identical), OXGR1 (20% identical), P2RY2 (19% identical), HCAR1 (19% identical), SUCNR1 (18% identical), P2RY1 (17% identical), and 3 more.
Diseases named in the same sentence as FFAR1 in open-access papers:
FFAR1 is named in the same sentence as 95 diseases in open-access papers, as found by Europe PMC text mining. Sharing a sentence is not in itself a finding about the gene and the disease. The quoted sentences say what the papers report.
type 2 diabetes (56 papers, 2007 to 2025). "In type II diabetes, increased levels of PA induce the loss of the β-cell function due to the involvement of FFAR1 in crosstalk with mTOR-Akt and IRS-1, altering insulin signaling." (PMID 39859502, 2025). "Since FFAR1 has been linked to beta-cell function and type 2 diabetes, it is possible that changes in insulin metabolism could impact on energy homeostasis and consequently BMI and body composition." (PMID 21552566, 2011). "It has been suggested that FFAR1 may play a role in insulin sensitivity, lipotoxicity and is associated with type 2 diabetes." (PMID 21552566, 2011). "Free fatty acid receptor-1 (FFAR1) agonists are promising candidates for therapy of type 2 diabetes because of their ability to normalize blood sugar levels during hyperglycemia without the risk of hypoglycemia." (PMID 37175725, 2023). "These unique characteristics of FFAR1 site-3 agonists make them an appealing potential therapy to treat type-2 diabetes." (PMID 36482991, 2022). "It is demonstrated for the first time that dietary ANC can enhance the activity of novel biomarkers FFAR1 and GK and potentially ameliorate type-2 diabetes comorbidities." (PMID 29995924, 2018). "The findings of this study open the possibility to use ANC from purple corn as candidates to activate FFAR1 and GK, known markers that when activated ameliorate type-2 diabetes and its complications." (PMID 29995924, 2018). "GPR40 (FFAR1) is a promising target for the managing type 2 diabetes (T2D)." (PMID 34555055, 2021). "FFAR1 plays a key role in the development of type 2 diabetes (T2D), and previous studies have indicated the importance of developing anti-diabetic therapies against FFAR1, although its role in the regulation of β-cell function remains unclear." (PMID 31426858, 2019). "Whether FFAR1 plays a role in β-cell compensation processes and is a possible link between energy surplus and β-cell failure in type 2 diabetes remains to be completely characterized." (PMID 29565831, 2018). "These properties suggest that FFAR1 could be a mediator of lipotoxicity and a potential candidate gene for Type 2 diabetes (T2D)." (PMID 17987108, 2007). "Small molecule agents that act as agonists for free fatty acid receptor 1 (FFA1, referred to as GPR40 before it was de-orphaned in 2003) is a promising class of drugs to treat type 2 diabetes mellitus (T2DM) which holds no risk of causing the development of hypoglycaemia." (PMID 34294008, 2021). "The same group confirmed a differentiation between partial FFAR1 ago-PAMs and full ago-PAMs by showing that the partial agonist MK-8666 while reducing food intake did not lead to a reduced total body weight in the Goto-Kakizaki rat model of type 2 diabetes, whereas the full ago-PAMs AP1 and AP3 did." (PMID 33578942, 2021). "The free fatty acid receptor 1 (FFAR1, formerly GPR40) is a potential target for the treatment of type 2 diabetes mellitus (T2DM)." (PMID 37376118, 2023). "Recently, free fatty acid receptor 1 (FFAR1, also known as GPR40) and glucokinase (GK) have attracted high interest as two novel targets for type-2 diabetes." (PMID 29995924, 2018). "The free-fatty acid receptor 1 FFAR1 (GRP40) is activated by medium- and long-chain fatty acids, plays an important role in glucose homeostasis and insulin secretion and is a long known and well-studied target for the treatment of type 2 diabetes." (PMID 31680947, 2019). "We show that 20-HETE is an FFAR1 agonist, which functions as an autocrine positive feed-forward regulator of GSIS, and that a reduced glucose-induced 20-HETE formation contributes to inefficient GSIS in type-2 diabetes." (PMID 29330456, 2018).
diabetes (44 papers, 2007 to 2025). "For example, GPR40/FFAR1 is abundantly expressed in pancreatic insulin-producing β cells and the intestine, thereby associating with the development of obesity and diabetes." (PMID 32365716, 2020). "The present study demonstrates a potential novel crosstalk in β-cells between FFAR1 and the Akt-mTOR pathway, a major signaling pathway involved in insulin regulation and diabetes." (PMID 31426858, 2019). "Considering the wide range of synthetic agonist of FFAR1 being developed to treat Diabetes, it became an interesting possibility to evaluate their repurposing for treating AD as well." (PMID 31105530, 2019). "FFAR1 deficiency protected from hepatic steatosis and hypertriglyceridemia and FFAR1 overexpression led to liver steatosis and, subsequently, impairment of islet function and diabetes." (PMID 29565831, 2018). "For example, two different mouse models of diabesity (diabetes and obesity), based on high fat diet or db/db mice, present a decrease in FFAR1 and BDNF expression in the hippocampus and brain cortex, that can be reverted by chronic administration of DHA or GW9608." (PMID 31105530, 2019). "In diabetes, 20-HETE induces insulin secretion and protects pancreatic islet cells from apoptosis by activating the free fatty acid receptor 1 (FFAR1/GPR40)." (PMID 39959811, 2024). "Among pancreatic GPCRs, Free Fatty Acid Receptor 1 (FFAR1, also referred to as GPR40) and GPR119 are popular examples of receptor targets that have received recent attention in the field of diabetes therapeutics." (PMID 32917053, 2020). "Whereas M3 receptors are expressed in a wide variety of tissues, precluding their selection as drug targets for diabetes, FFAR1 (GPR40) and FFAR4 (GPR120) are Gαq-coupled long-chain fatty acid receptors that have been a focus for small molecule development." (PMID 26661410, 2016). "Among them, the free fatty acid receptor (FFAR) FFAR1 (GPR40), FFAR2 (GPR43), FFAR3 (GPR41), and FFAR4 (GPR120) may bridge the genetic and environmental aspects of diabetes (14, –, 18)." (PMID 37787527, 2023).
Obesity (29 papers, 2013 to 2024). Accumulation of substantial excess body fat. "Collectively, how changes associated with an obesity phenotype, such as inflammation, proliferation and cell metabolism, are differentially modulated by FFAR1 or FFAR4 in obesity remains unknown." (PMID 33256729, 2020). "Treatment of adipocytes with agonists TUG-891 (selective for the FFAR4) and GW9508 (selective for FFAR1/GPR40) induce deoxyglucose uptake, thus indicating a promising role to counteract obesity and insulin resistance." (PMID 36831123, 2023). "Accordingly, we posit that free fatty acid receptors (FFAR1 and FFAR4) can modulate E–C coupling in HASM cells and play a role in obesity-associated AHR." (PMID 33256729, 2020). "We hypothesized that FFAR1 modulate excitation–contraction (EC) coupling in HASM cells and play a role in obesity-associated airway hyperresponsiveness." (PMID 33256729, 2020). "Plasma free fatty acids are elevated in obesity, therefore prolonged exposure to free fatty acids may desensitize and modulate FFAR1 functions in obese individuals." (PMID 33256729, 2020). "FFAR1 inhibition and/or an increase of cAMP signaling in the hypothalamus could offer potential therapeutic targets to counteract the effects of dietary or genetically induced obesity on depression." (PMID 31076569, 2019). "Although this study originated from our interest in obesity, the FFAR1 agonist TAK875 has no differential effect on MLC phosphorylation in obese- and non-obese donor derived HASM cells." (PMID 33256729, 2020). "Taken together, our findings identified the FFAR1 agonist TAK875 as a novel bronchoprotective agent that warrants further investigation to treat difficult-to-control asthma and/or airway hyperreactivity in obesity." (PMID 33256729, 2020). "Second, we examined the anti-obesity effect of T-3601386 in a diet-induced obese (DIO) model and conducted c-Fos immunohistochemistry in the NTS after T-3601386 administration, followed by the confirmation of their GPR40 dependence using Ffar1-/- mice." (PMID 31525244, 2019). "First, we identified gene sets related to the function of each obesity-related serum factor: HG/HI (Insr, Irs1, Rps6kb1, Slc2a4, Slc2a5, Slc2a1), TNF-α (Tnfrsf1a, Tradd, Traf2, Fadd), IL-6 (Il6ra, Il6st, Jak1), and fatty acids (PA, LA, Chol; Ffar1, Ffar4, Ppara, Pdk4, Pgc1a)." (PMID 37047207, 2023). "However, our in vitro findings may not predict whether FFAR1 function in HASM cells is altered in obesity in vivo." (PMID 33256729, 2020).
Insulin resistance (28 papers, 2011 to 2024). Increased resistance towards insulin, that is, diminished effectiveness of insulin in reducing blood glucose levels. "We previously showed that Gpr40, also known as Ffar1, mediates high fat diet-induced hyperinsulinemia, and additionally our study suggested that hyperinsulinemia, hepatic Cd36 expression, hepatosteatosis, and insulin resistance were associated." (PMID 26085100, 2015). "Saturated fatty acids reduce FFAR1 expression and induce insulin resistance, potentially contributing to lipotoxicity." (PMID 38774257, 2024). "In monogastrics, FFAR1 plays a role in CLA-induced fatty liver but it is important to prevent CLA-induced inflammation and insulin resistance in the brain, as observed in Ffar1-knockout mice, indicating somewhat tissue-specific effects of FFAR1." (PMID 33292523, 2020). "It is important to understand the exact mechanism of action of FFAR1 and the physiological relevance of our observations to better understand how FFAR1 promotes insulin resistance and the development of T2D." (PMID 31426858, 2019). "There has been increased interest in FFAR1 for the development of anti-diabetic targeted therapies for the treatment of T2D since studies have demonstrated its role in insulin resistance." (PMID 31426858, 2019). "Knowledge of this interplay could further aid our understanding of how FFAR1 affects insulin sensitivity, insulin resistance, and overall β-cell function in T2D." (PMID 31426858, 2019). "FFAR-1 enhances specific pancreatic β-cell activity, while in T2D, this activity is downregulated, resulting in FFAR-1 inhibition and insulin resistance." (PMID 36900540, 2023). "Only a few studies exist on GPR119, free fatty acid receptor 1 (FFAR1/GPR40) and 4 (FFAR4/GPR120), and the bile acid receptor GPBAR1 (TGR5) as a developer of insulin resistance and β-cell dysfunction, receiving particular attention as targets for therapeutic interventions in diabetic patients." (PMID 35885041, 2022). "Free fatty acid receptor 1 (FFA1) has been recognized to mediate insulin secretion, and pioglitazone has direct effects on glucose-stimulated insulin secretion in addition to the reversion of insulin resistance." (PMID 30863781, 2019).
breast carcinoma (13 papers, 2013 to 2023). "In MCF-7 and MDA-MB-231 breast carcinoma lines, OA enhanced metastasis and cellular proliferation through activation of free fatty acid receptor 1 (FFAR1) and FFAR4 receptors that are activated by medium-chain FAs like OA." (PMID 35294666, 2022). "We have previously shown that oleate promotes breast cancer cell growth via the FFA receptor FFAR1/GPR40 and PI-3-kinase activation and that upregulation of cellular triacylglycerol-FFA cycling by oleate is associated with long-term serum-free survival of human breast-cancer cells." (PMID 33805661, 2021). "In some tumors, FFAR1 and FFAR4 have similar effects, and the activation of FFAR1 and FFAR4 can promote the proliferation and migration of breast cancer cells and enhance the growth of colon cancer cells." (PMID 35785152, 2022). "OA stimulated survival and proliferation through the activation of a free fatty acid receptor 1 (FFAR1)-dependent MAPK pathway and PI3K pathway, induced invasion and migration through MMPs and FAK-Src activation and reduced apoptosis in an aggressive breast cancer cell line, MDA-MB-231 cells." (PMID 27589390, 2016).
Hyperglycemia (13 papers, 2013 to 2025). An increased concentration of glucose in the blood. "GPR40 (also known as a free fatty acid receptor 1) is highly expressed in pancreatic β-cells and mediates fatty-acid-induced enhancement of insulin secretion during hyperglycemia." (PMID 26561346, 2015).
Hyperinsulinemia (12 papers, 2007 to 2021). An increased concentration of insulin in the blood. "FFAR1 plays an important role in FFA-induced hyperinsulinemia." (PMID 31426858, 2019). "Also, studies in GPR40/FFAR1-deficient mice confirmed a role for FFAs in the amplification of insulin secretion; these mice did not develop hyperinsulinemia nor glucose intolerance when given a high-fat diet, since this deficiency protected from the harmful metabolic effects of high-fat feeding." (PMID 29565831, 2018).
Hepatic steatosis (10 papers, 2011 to 2025). Steatosis is a term used to denote lipid accumulation within hepatocytes. "The mechanism of the hepatoprotective effect of QS-528 is not known, but it can be assumed that, in a model of metabolic liver damage, it resolves hepatic steatosis through stimulation of the AMP-activated protein kinase (AMPK) signaling pathway as other FFAR1 agonists." (PMID 37376118, 2023).
Hypoglycemia (10 papers, 2011 to 2023). A decreased concentration of glucose in the blood. "It is worth noting that expression of the gene encoding FFAR1 increases with increasing blood glucose concentrations and decreases after blood glucose level normalization, which is considered to prevent hypoglycemia when using agonists of this receptor." (PMID 37175725, 2023). "Our theoretical analysis shows that activators of GLP-1, GIP and FFAR1/GPR40 receptors may have a low risk of hypoglycemia because they need a concomitant increase in [Ca2+]c for activation whereas an activator of muscarinic receptors can lead to hypoglycemia." (PMID 27138453, 2016).
insulinoma (8 papers, 2008 to 2020). "Here, we found similar FFAR1 density in another model of pure beta cells (insulinoma xenografts) as in islet homogenates." (PMID 28409274, 2017). "However, other studies showed that upregulation of FFAR1 protects against lipotoxicity in rat insulinoma (INS-1) cells, while FFAR1 overexpression in islet beta cells improves GSIS and glucose tolerance in vivo." (PMID 30061862, 2018). "[3H]TAK-875 (fasiglifam), which is a small molecule FFAR1 agonist that reached clinical phase 3, exhibited high non-specific off-target binding in insulinoma xenograft tissue, demonstrating the difficulties involved in molecular imaging with lipophilic compounds." (PMID 28409274, 2017).
metabolic syndrome (6 papers, 2011 to 2025). A cluster of metabolic risk factors for CARDIOVASCULAR DISEASES and TYPE 2 DIABETES MELLITUS. "No BS for either KLF14 or SREBF1 was identified in the promoters of MC4R, 5-HT2C, MC3R, S1PR2, FFAR1/GPR40, and HCR2 within this database, despite their known association with metabolic syndrome." (PMID 40243421, 2025). "The role of FFAR1 in the CNS is not known, but it is hypothesised that this may be a mechanism by which FFAs are involved in the hypothalamic regulation of metabolism and its expression in omental adipocytes implicates it in the development of the metabolic syndrome." (PMID 21552566, 2011).
Anxiety (5 papers, 2018 to 2023). Intense feelings of nervousness, tension, or panic often arise in response to interpersonal stresses. "Recent reports show that GPR40/FFAR1 may be also associated with anxiety- and depression-related behavior regulated by the increment of noradrenaline in the brain." (PMID 33923318, 2021). "An increase in noradrenaline was also observed in FFAR1-KO mice brain regions were the expression of the receptor was shown to be higher, suggesting a role in anxiety and depression symptoms." (PMID 31105530, 2019). "Actually, FFAR1-KO mice manifested no evident alteration of social or motor behavior, although they showed a reduction anxiety-like responses." (PMID 31105530, 2019).